NSD2 (nuclear receptor binding SET domain protein 2)
Diseases named in the same sentence as NSD2 in open-access papers (continued):
Sharing a sentence is not in itself a finding about the gene and the disease.
cancer (continued). "Top H3K36me2 regions contained twice less CpG islands and 3.5 less genes per Kb than regions with low H3K36me2, suggesting that the absence of CpG islands and gene bodies might favor the spread of this mark in cancer cells that express high levels of NSD2." (PMID 27604143, 2016). "Therefore, combinatorial therapies using NSD2 inhibitors together with MEK or BRD4 inhibitors are likely to be effective in fighting RAS-dependent cancers with NSD2 overexpression." (PMID 27604143, 2016). "Indeed, several cancer lines bringing NSD2 translocations, showed an up-regulation of histone 3 lysine 36 (H3K36) dimethylation." (PMID 24912534, 2014). "Furthermore, overexpression of wild-type NSD2 is sufficient to transform NSD2-/- cancer cells in vivo and in mouse embryonic fibroblasts (MEFs)." (PMID 24622842, 2014). "Herein we show that NSD2 EK plays an essential role in reorganizing the 3D genome through a striking reliance on compartment reorganization and uncover a convergence on pathways vital to cancer progression, indicating the translational relevance of our findings." (PMID 37016431, 2023). "Similarly, a meta-analysis of 1,755 samples from 22 published microarray gene expression studies in 15 different cancers using Oncomine database also revealed that NSD2 displayed the most correlated transcriptional expression with EZH2 in a majority of studies (82%)." (PMID 33665162, 2020). "Given that the expression levels of NSD2 are dynamically regulated during the cell cycle and that NSD2 is overexpressed in various types of cancer cells, the role of NSD2 might vary in cell cycle‐ and dose‐dependent manners as well as in a genomic locus‐specific manner." (PMID 32573059, 2020). "This particular mode of action suggests that NSD2 could also contribute to boost the transcriptional responses mediated by other oncogenic pathways responsible for the establishment or maintenance of enhancer regions in other types of cancer." (PMID 27604143, 2016). "Additionally, NSD2 could potentially contribute to boost the transcriptional outputs of other oncogenic pathways different from RAS depending on the cancer type." (PMID 27604143, 2016). "Together, these findings highlight gain-of-function mutations in NSD family genes as critical epigenetic drivers of tumorigenesis, positioning NSD2 and NSD3 as promising biomarkers and therapeutic targets for cancer treatment." (PMID 41301842, 2025). "In this cancer model, H3K36M interacts with NSD2 and NSD3, thus inhibiting their enzymatic activities toward H3K36 methylation." (PMID 41301842, 2025). "Inactivation of NSD2 also engendered increased dependency on its paralog NSD1, which independently maintained AR and MYC hyper-transcriptional programs in cancer cells." (PMID 38464251, 2024). "The nuclear receptor-binding SET domain (NSD), a family of histone lysine methyltransferases, including NSD1, NSD2/WHSC1/MMSET, and NSD3/WHSC1L1, have been identified as potential therapeutic targets for cancer." (PMID 39163297, 2024). "As shown, the frequencies of genetic alterations in NSD1, NSD2, and NSD3 across cancers were 5%, 3%, and 7%, respectively." (PMID 37062069, 2023). "NSD2, a member of the NSD histone methyltransferase family, is highly expressed in a variety of malignant tumors." (PMID 37959819, 2023). "In this approach, some studies have already described important molecular alterations in the NSD1, NSD2 and NSD3 genes and their role in cancer initiation and development." (PMID 32153656, 2020). "Previously, it has been reported that NSD2 would mediate cell migration and invasion via EMT process, which performed crucial functions in cancer progression and metastasis 7-9." (PMID 31692936, 2019). "Our data suggest that NSD3 is a compelling drug target for cancer and that NSD1/NSD2/NSD3 structural similarity should be used for structure-based drug design to develop a new class of histone methyltransferase inhibitors for cancer." (PMID 24874471, 2014).
cancer (continued). "The NSD family of HMTases comprised of three members (NSD1, NSD2/MMSET/WHSC1, and NSD3/WHSC1L) are oncogenes aberrantly expressed in several cancers, suggesting their potential to serve as novel therapeutic targets." (PMID 25494638, 2014). "NSD2 is an H3K36 methyltransferase and has been considered a cancer-promoting factor." (PMID 41760632, 2026). "Particularly, NSD2 and NSD3 are frequently overexpressed in various cancers." (PMID 39741006, 2025). "Taken together, this study highlighted the role of Nsd2 in GCB positive selection by enhancing both BCR signaling and T cell help, which may have implications in cancer." (PMID 40586874, 2025). "NSD2-induced H3K36me2 also upregulates key enzymes in glucose metabolism, including hexokinase 2 (HK2) and glucose-6-phosphoate dehydrogenase (G6PD), in endocrine therapy-resistant cancer cells." (PMID 41301842, 2025). "With super-enhancers hijacking essential transcription factors (MYC) and chromatin remodelers (NSD2), it may not be surprising that the increased expression and presence of the translated protein could indirectly drive the appearance of H3K4me3-BD over other cancer-associated genes." (PMID 34933939, 2022). "In other primary cancer cells, pri-Can-2 and pri-Can-3, as well as in established CRC cell lines (HT-29 and HCT-116), stable NSD2 silencing by the shNSD2-Seq-1 similarly increased caspase-3 activity and induced mitochondrial depolarization (JC-1 green monomers accumulation)." (PMID 34671018, 2021). "Additionally, expression of H3K36M impairs adipogenesis in preadipocytes and cell proliferation in fibrosarcoma cancer cells, respectively, which can both be recapitulated by depleting NSD2, but not SETD239,40." (PMID 37602556, 2023). "However, the effects of other frequent missense cancer mutants in NSD2 and its paralog NSD1 are not well understood." (PMID 37150325, 2023). "Four CRs (TRRAP, EP300, NSD2 and MSH6) having synthetic lethal interactions with MAP2 were integrated as a MAP2 CSL module in COAD, where MAP2 was affected by two taxnes (Paclitaxel and Docetaxel).These four CRs play roles in cell cycle, notch signaling pathway and mismatch repair in human cancers." (PMID 36180906, 2022). "Furthermore, NSD2 protein was over-expressed in ccRCC tissues, but not correlated with pathological grading, probably due to the limited number of cancer samples." (PMID 31692936, 2019). "NSD2 also methylates non-histone proteins including AURKA and PTEN, which regulate cellular sensitivity to DNA damage and thus increase cancer proliferation." (PMID 32826945, 2020). "Both approaches might be useful for knocking down NSD2 in vivo in PAH models, although the transfer of cancer chemotherapy approaches to PAH is not always a useful therapeutic strategy." (PMID 33287230, 2020).
tumor (75 papers, 2013 to 2026). "To elucidate the mechanisms underlying the tumor-promoting roles of NSD2, we analyzed the differentially expressed genes after NSD2 overexpression using RNA sequencing." (PMID 40097917, 2025). "By analyzing RNA sequencing from TCGA and experimental models, the authors showed that high NSD2 expression was associated with an immunosuppressive tumor microenvironment." (PMID 40586874, 2025). "The tumor microenvironment associated with high NSD2 expression was characterized by reduced major histocompatibility complex class I (MHC-I) expression and limited CD8+ T cell infiltration." (PMID 40586874, 2025). "Among NSD family members, NSD2 has been more widely implicated as a regulator of immune cells in the tumor microenvironment." (PMID 41301842, 2025). "AR chromatin immunoprecipitation with sequencing (ChIP-seq) in NSD2-deficient LNCaP cells showed a dramatic and complete off-loading of the AR protein from over 40,000 genomic sites that comprise over 65% of the tumor cistrome." (PMID 39251788, 2024). "Remarkably, the “hotspot” E1099K mutation within the catalytic domain of NSD2 is found in 14% of pediatric ALLs and other neoplasms, such as lung adenocarcinoma, colon cancer, and thyroid tumors." (PMID 37051671, 2023). "To determine whether NSD2 was related to tumor immunity, we next evaluated the association between the immune infiltration and the 28 types of TIICs in PCa from the ssGSEA." (PMID 38062230, 2023). "Similar mechanisms might also apply to the E1099K and T1150A mutations in NSD2, providing critical insights into the role of NSD2/3 in driving tumor progression." (PMID 37051671, 2023). "EZH2-driven H3K27me3 silences these microRNAs, thereby stabilizing NSD2 expression and elevating H3K36me2, which promotes tumor growth and metastasis." (PMID 41601922, 2026). "Hepatocyte-specific NSD2 overexpression suppresses the proliferation of tumor cells in DEN-treated mice." (PMID 41760632, 2026). "RNA-seq, ChIP-seq, and orthotopic tumor models were employed to decipher the downstream mechanisms of NSD2 responsible for HCC development." (PMID 41760632, 2026). "Consistently, the expression of ULK1 was significantly increased in TNBC tumor tissues and positively correlated with NSD2 and H3K36me2." (PMID 40097917, 2025). "It has been reported that upregulation of NSD2 is positively correlated with tumor cell proliferation and tumor angiogenesis." (PMID 38400589, 2025). "Collectively, this study demonstrated a tumor suppressor like role for NSD2 in CRC that can be leveraged for better immunotherapy outcome by enhancing the NSD2 activity." (PMID 40586874, 2025). "In vivo, NSD2 inhibition reduced tumor growth in immunocompetent mice and increased frequency of CD8+ T cells, whereas no tumor suppression was observed in immunodeficient mice, underscoring the importance of a functional immune system." (PMID 40586874, 2025). "More importantly, 57 TNBC tumor tissues expressed significantly elevated NSD2 and H3K36me2 protein levels compared to the receptor-positive tumors." (PMID 40097917, 2025). "Widely overexpressed in diverse malignancies, NSD2 (nuclear receptor binding SET domain protein 2) orchestrates tissue-level immunosuppression and promotes the formation of immunosuppressive niches in tumor microenvironments." (PMID 40509092, 2025). "We evaluated the expression of Ki67 and CD31 considering that NSD2 knockout significantly inhibited tumor growth." (PMID 38400589, 2025). "This inhibition of Ki67 and CD31 suggested that tumor proliferation and angiogenesis decreased with NSD2 knockout in the colon." (PMID 38400589, 2025). "Here, we show that the tumor-specific enhancer circuitry of AR is critically reliant on the activity of Nuclear Receptor Binding SET Domain Protein 2 (NSD2), a histone 3 lysine 36 di-methyltransferase." (PMID 38464251, 2024). "NSD2 has been identified as a key tumor suppressor during pancreatic tumorigenesis and as a novel negative regulator of NF‐κB signaling." (PMID 38889281, 2024).
tumor (continued). "This translocation universally leads to high expression of histone methyltransferase nuclear SET domain-containing 2 (NSD2), also known as MMSET, and it plays a pivotal role in the evolution of MM, tumor progression, and genomic instability." (PMID 38254774, 2024). "Together, the study reveals the important tumor suppressor role of NSD2 and multiple mechanisms by which NSD2 suppresses both p65 phosphorylation and downstream transcriptional activity during pancreatic tumorigenesis." (PMID 38889281, 2024). "We have identified NSD2 as a key tumor suppressor during pancreatic tumorigenesis and as a novel negative regulator of NF‐κB signaling." (PMID 38889281, 2024). "APC (p = 1.7e-20), BCL9 (p = 0.0006), CREBBP (p = 8.5e−5), FLCN (p = 1.39e−7), NSD2 (p = 0.002), and EP300 (p = 1.42e−6) all had significantly higher mutation rates in MSLN low expressing tumor samples compared to MSLN high expressing tumor samples." (PMID 39174744, 2024). "Here, the study demonstrates that NSD2 acts as a putative tumor suppressor in Kras‐driven pancreatic tumorigenesis." (PMID 38889281, 2024). "During tumor formation, high NSD2 expression catalyzes H3K36me2 at nuclear factor kappa B (NF-kB) target gene promoters to activate the NF-kB pathway, thereby promoting tumor growth." (PMID 38236723, 2024). "Here, we show that tumor-specific AR enhancers are critically reliant on H3K36 dimethyltransferase activity of NSD2." (PMID 39251788, 2024). "Studies in cervical cancer revealed that NSD2 promotes tumor progression and metastases by inducing transforming growth factor-beta (TGF-β)-mediated immunosuppression." (PMID 38062230, 2023). "Specifically, NSD1 acts as an apparent tumor suppressor, whereas NSD2 primarily promotes oncogenesis." (PMID 37602556, 2023). "The results are strongly consistent with our findings suggesting that NSD2 regulates various immune molecules in the tumor microenvironment of PCa, thereby affecting CD4+ and CD8+ T immune cell infiltration." (PMID 38062230, 2023). "High NSD2 expression was positively correlated with the infiltration level of CD4+ tumor-infiltrating lymphocytes (TILs) and negatively correlated with that of CD8+ TILs." (PMID 38062230, 2023). "Western blotting assays of tumor lysates found that levels of NSD2 protein and H3K36me2 levels were depleted in shNSD2 AAV-injected tumors." (PMID 34671018, 2021). "The mRNA expression study documented a significant increase in the levels of 4 HMTs viz MLL1, MLL2, SMYD2 and NSD2 in tumor tissues." (PMID 31160694, 2019). "A number of histone methyltransferases, including Setd3, Setd5, Suv39h2, Smyd3, Prmt3, Prmt6, Nsd1, and Nsd2, were up-regulated in metastases compared to disseminated tumor cells or primary tumors." (PMID 23520493, 2013). "Our results identify NSD2 as a tumor suppressor in the development of HCC." (PMID 41760632, 2026). "Similarly, we also observed a significant decrease in NSD2-knockdown BT549 tumor growth in the mice as compared to control." (PMID 40097917, 2025). "Given that NSD2 plays a more important role in promoting TNBC cell autophagy, we then investigated whether the tumor-promoting role of NSD2 is related with autophagy." (PMID 40097917, 2025). "Furthermore, NSD2 has also been shown to be important in the context of the regulation of anti-tumor immune response." (PMID 40586874, 2025). "In PCa, coordinated expression of EZH2 and NSD2 is found to promote tumor progression." (PMID 39917394, 2025).
tumor (continued). "Thus, based on the impact on anti-tumor immunity mediated by NSD2 or its downstream effectors can be further explored as targets for enhancing immunotherapy responses." (PMID 40586874, 2025). "Moreover, knock-down of NSD2 in cell lines leads to reduced cellular adhesion and tumour growth as well as reduced tumour formation in xenograft models." (PMID 40116454, 2025). "NSD2 regulates Wnt‐ and NF‐kB‐related pathways to support tumor growth and survival." (PMID 38400589, 2025). "We observed that knockout of NSD2 significantly decreased 4T1 orthotopic tumor growth." (PMID 40097917, 2025). "NSD2 acts as a putative tumor suppressor in Kras‐driven pancreatic tumorigenesis." (PMID 38889281, 2024). "NSD2 is a critical molecule in cell senescence, T cell differentiation, cell proliferation, and tumor metastasis." (PMID 38236723, 2024). "Furthermore, high expression of NSD2 was also significantly correlated with tumor stage (p = 0.0001), lymph node metastasis (p = 0.0001) and distant metastasis (p = 0.001)." (PMID 38062230, 2023). "Furthermore, the Immuno-Oncology-Biological-Research (IOBR) software package was used to analyze the potential roles of NSD2 in the tumor microenvironment." (PMID 38062230, 2023). "During tumor growth, reprogrammed glucose metabolism is involved to meet the demand of glycolytic intermediates for macromolecule biosynthesis, during which the NSD2 has been reported to play a role by regulating key glucose metabolism regulators, such as TIGAR, HK2, and G6PD." (PMID 35354439, 2022). "Given that NSD1 and NSD2 have been linked to various aspects of HPV- HNSCC, including epigenetic alterations, immune status of the tumor, and predicting patient outcome at specific subsites, we investigated the roles of NSD1 and its two paralogs NSD2 and NSD3 in HPV+ HNSCC." (PMID 33588906, 2021). "NSD2 is involved in many types of tumours through enhancing H3K36me2 expression." (PMID 30334333, 2019). "However, targeting NSD2 clinically is likely to impact tumour cell features globally, and characterising the downstream effects of NSD2 in a model system may therefore improve the development of therapeutic strategies." (PMID 40116454, 2025). "Based on this, the examination of IGH::NSD2 fusion transcripts in peripheral blood samples cannot definitively determine whether the signal originates from circulating tumor cells derived from the bone marrow or if it indicates the presence of extramedullary manifestations." (PMID 38254774, 2024). "Subsequent studies found that NSD2 inhibition increased phenotypic transformation of immune cells, such as infiltration of cytotoxic T cells and NK cells and local regulation of different myeloid cell subpopulations present within the tumour, as well as translocation of key signalling pathways." (PMID 38062230, 2023). "Furthermore, BRCA1 protein level was decreased in bone marrow tumor, while NSD2 level was elevated." (PMID 32826945, 2020). "NSD2 and its H3K36 methyltransferase activity recruit AR to tumor-specific enhancers, where it cooperates with pioneer factors such as FOXA1, HOXB13, and ETS, redistributing AR binding and amplifying oncogenic signaling." (PMID 41601922, 2026). "Specifically, NSD2 inhibition in HPV+ tumors restores epithelial differentiation, offering a potential strategy to arrest tumor progression." (PMID 41507992, 2026). "Given the tumor-promoting effects of NSD2 in TNBC, we took advantage of a pharmacological approach to suppress NSD2 expression and activity." (PMID 40097917, 2025). "The short isoforms of NSD2 and NSD3, which lack the catalytic SET domain, retain potent tumor-promoting capabilities by functioning as chromatin scaffolds, transcriptional adaptors, and protein interaction hubs." (PMID 41301842, 2025). "NSD2 catalyzes STAT3 methylation, which contributes to the activation of the STAT3 pathway and tumor angiogenesis." (PMID 38400589, 2025).